CXCL2 (C-X-C motif chemokine ligand 2)
Diseases named in the same sentence as CXCL2 in open-access papers (continued):
Sharing a sentence is not in itself a finding about the gene and the disease.
COVID-19 (56 papers, 2020 to 2025). A disease caused by infection with severe acute respiratory syndrome coronavirus 2. "High levels of these molecules, detected after macrophage treatment with VLPs (TNFα, IL-1β, CCL8, CXCL8, CXCL9, CXCL16, CXCL1, and CXCL2), were shown to correlate with severe COVID-19 in other studies." (PMID 38664730, 2024). "For example, previous research has shown that the COVID-19-associated ARDS exhibited higher levels of plasma CCL5, CXCL2, and CXCL10 compared to the non-COVID-19 ARDS patients." (PMID 38745657, 2024). "We also examined the expression of previously reported inflammatory cytokines (TNF, IL6, IL1B, CCL3, CCL4 or CXCL2) produced by circulating monocytes in patients with COVID-19." (PMID 37363730, 2023). "All of the 6 intersected genes have been reported to associate with COVID-19, including FGFR3, TP63, CXCL2, CCL20, IL1B and CXCL8." (PMID 37497545, 2023). "qRT-PCR confirmed the expected induction of immune-response markers CXCL2 and IL-6 in COVID-19 patients from this cohort." (PMID 35998224, 2022). "Of the proinflammatory cytokines, the following are of particular interest: CCL20, which has been associated with the first severe acute respiratory syndrome coronavirus (SARS-CoV), and IL-1B, CXCL1, CXCL2, and CXCL8, which are associated with COVID-19." (PMID 32752138, 2020). "The results of network pharmacology analysis showed that Yinqiao powder may inhibit inflammatory responses by suppressing IL-6, CXCL2, TNFα, NF-κB, etc., in the treatment of COVID-19." (PMID 36467981, 2022). "The network pharmacology results showed that Yinqiao powder may inhibit the inflammatory response by suppressing IL-6, CXCL2, TNFα, NF-κB, etc., in the treatment of COVID-19." (PMID 36467981, 2022). "Subsequently, Paxlovid was analyzed against the core targets of LUAD/COVID-19 (CXCL2, CCL2, IL12B, CSF3, LBP, IL6, CXCL10) and Paxlovid, and the results showed that IL-6, IL12B, LBP and Paxlovid could be combined." (PMID 36157452, 2022). "In addition, their data suggest that neutrophils could also contribute to the disease observed in COVID-19 patients, as demonstrated by CXCL2 and CXCL8 induction, differently from influenza virus infection." (PMID 35369457, 2022). "Conversely, in silico perturbation of COVID-19 human blood cells using human-Geneformer model predicted that deletion of genes CXCL2, IFITM3, and CCL20 would revert the COVID-19 cells towards a normal state." (PMID 40106407, 2025). "The interaction between the CXCL family (CXCL1, CXCL2, and CXCL8) is also considered a COVID-19 severity-specific molecular interplay." (PMID 40163554, 2025). "CCL3, CCL5, CXCL2, and CXCL10 have been reported to be increased in patients with severe COVID-19-related acute respiratory distress syndrome (ARDS)." (PMID 38584257, 2024). "The main inflammatory cytokines and chemokines widely produced by patients with severe forms of COVID-19 are IL-6, IL-8, IL-1β, TNF-alpha, IFN-gamma, MIP1α and 1β, CCL2, CCL5, CCL20, CXCL1, CXCL2, CXCL8, CXCL10, and CXCL17." (PMID 39768136, 2024). "We note the differential expression of many inflammatory CC chemokines (CCLs) in severe COVID-19, including CCL2, CCL3, CCL8, CCL3L1 and CCL7, and CXC chemokines such as CXCL2 and CXCL8." (PMID 39187683, 2024). "A higher expression of chemokines (CXCL1, CXCL2, CXCL3, CXCL8 and CXCL16) were also found in the CD4+ TCM and Classical Monocytes in the COVID-19 patients." (PMID 36532041, 2022). "A significant increase in CXCL2, CXCL8, CXCL9, and CXCL16 levels was reported in COVID-19 positive patients with generalized inflammation." (PMID 36016187, 2022). "The overexpression of neutrophil chemoattractants such as CXCL1, CXCL2, CXCL3, CXCL5, IL-8 (CXCL8), and CCL20 in the lungs of COVID-19 patients suggest that these cells can express neutrophil chemokines after SARS-CoV-2 infection." (PMID 34737734, 2021). "In consistence with previous observations, IL-6, CCL2, CXCL2, CXCL10, and IL-8 were significantly elevated in COVID-19 samples." (PMID 34103487, 2021).
COVID-19 (continued). "These included IL-6, TNF-α, CCL5, and CXCL2 with expression levels significantly surpassing those observed in SARS-CoV-2 and HKU4 controls, which were positively related to severity in COVID-19 patients." (PMID 40774246, 2025). "Similarly, several studies have reported the overexpression of chemokines in COVID-19, such as C-C motif chemokine ligands 8 and 11 (CCL8 and CCL11), and C-X-C motif chemokine ligands 2, 8, 9, and 16 (CXCL2, CXCL8, CXCL9, and CXCL16)." (PMID 40722944, 2025). "Increased levels of CXCL2 and CXCL8 have been shown through Transcriptional analysis of peripheral blood mononuclear cells and BALF from COVID-19 patients, to contribute to the recruitment of neutrophils to the lung, which then exacerbate the inflammatory response." (PMID 34737734, 2021). "We show that plasma CXCL2, CXCL10, CCL5, CD40 ligand, IL-10, and GM-CSF concentrations and ELF CXCL1, CXCL10, granzyme B, TRAIL, and EGF concentrations were found in greater concentrations in COVID-19 than in non-COVID-19 ARDS patients." (PMID 33138839, 2020). "Consistently, in this study we found the expression of a large number of cytokines are significantly elevated in COVID-19 patients BALF samples compared to control, including pro-inflammatory cytokines CXCL1, CXCL2, CXCL6, CXCL8, CXCL10/IP-10, CCL2/MCP-1, CCL3/MIP-1A and CCL4/MIP1B." (PMID 32228226, 2020). "Interestingly, treatment of monocytes with the STAT-inhibitor and COVID-19 drug Ruxolitinib not only reduced the expression of STAT-targets CXCR4 and NAMPT, but also increased the expression of proinflammatory markers CXCL8 and CXCL2." (PMID 35998224, 2022). "Concordantly, for downstream genes of AP-1, the expression levels of some chemokine genes (e.g., CCL2, CXCL1, CXCL2, and CXCL10) were downregulated, while the expression levels of immune negative regulation genes (e.g. BCL3, NFKBIA, SOCS3, and TNFAIP3) were upregulated during the COVID-19 recovery." (PMID 33361761, 2020). "Such chemokines are able to recruit polymorphonuclear cells, such as monocytes, memory T cells, NK cells, and neutrophils in the site of infection and pregnant COVID-19 women were characterized by higher levels of CCL4, CCL5, and CXCL2 if compared with pregnant women without infection." (PMID 34326336, 2021). "COVID-19 ARDS patients had significantly higher plasma concentrations of CCL5 (p = 0.025) and non-significantly higher plasma concentrations of CXCL2 (p = 0.094), CXCL10 (p = 0.287), CD40 ligand (p = 0.125), IL-10 (p = 0.232), and GM-CSF (p = 0.332) compared with non-COVID-19 ARDS patients." (PMID 33138839, 2020).
colitis (53 papers, 2012 to 2025). Inflammation of the colon. "TRPM2-deficient mice are more resistant to chronic experimental colitis due to defective chemokine (C-X-C motif) ligand 2 (CXCL2) production by monocytes and reduced neutrophil infiltration." (PMID 23631390, 2013). "For instance, TRPM2 expression correlates with monocyte-derived CXCL2 secretion and neutrophil infiltration in colitis, while TRPM2-deficient mice show reduced IL-12, interferon levels, and nitric oxide synthase expression in splenic macrophages during Listeria infection." (PMID 41293090, 2025). "The results demonstrated that CXCL2, a major chemokine involved in colitis progression, showed a significant reduction following BA and BI interventions in a DSS induced mouse model." (PMID 41036227, 2025). "Consistently, higher levels of pro‐inflammatory Il1b, Il6, Tnf, Cxcl2 and Cxcl10 mRNA were detected in the colon of Otub2–/– mice, further consolidating the more severe colitis in these mice." (PMID 39358938, 2024). "When compared to control colitis animals, the expressions of inflammatory markers such as IL-1β, IL-4, IL-6, and Cxcl2 were significantly lower in mice receiving IAA treatment." (PMID 39068517, 2024). "In an acute trinitrobenzene sulfonic acid (TNBS)-induced colitis model, the production of CXCL2 in the colon and its severity are reduced in Il17ra–/– mice." (PMID 38312837, 2024). "In the Con-DSS group, the expression levels of pro-inflammatory cytokines (TNF-α, IL-6, and IFN-γ) and those of neutrophil-attracting chemokine CXCL2 were increased by colitis." (PMID 35688905, 2022). "Otherwise, PGE2 has been demonstrated to induce CXCL1 and CXCL2 expression in the colonic mucosa and tumors, which leads to the chemoattraction of MDSC and promotes the colitis-associated tumorigenesis." (PMID 34689842, 2021). "The mRNA expression level of Cxcl2 and Il-1β in the colons of WT colitis mice was markedly elevated on day 7 (Cxcl2; 0.0 ± 0.0 in WT normal, 5.3 ± 1.7 in WT colitis; p < 0.01, Il-1β; 0.4 ± 0.1 in WT normal, 6.6 ± 2.1 in WT colitis; p < 0.01)." (PMID 33192516, 2020). "In the present study, the infiltration of neutrophils and the upregulation of CXCL2 and IL-1β observed in colonic tissues of colitis mice were significantly suppressed in the IL-4Rα-/- mice." (PMID 33192516, 2020). "The pro‐inflammatory cytokines IL1A, IL1B, IL6, and CSF3 and chemokines CXCL1 and CXCL2 were significantly increased, and the frequency of CD11b+Ly6G+ neutrophils was higher in CD11c‐Cre+Rab32f/f colitis mice." (PMID 30338217, 2018). "Ltd.)reduced basal levels of pro-inflammatory cytokines and chemokines like monocyte chemotactic protein-2 (MCP-2), chemokine (C-X-C motif) ligand 2 (CXCL2) and improved epithelial barrier function in mucin deficient (Muc2−/−) animals or DSS-induced colitis." (PMID 29966337, 2018). "It has been shown that TRPM2 channels control neutrophil infiltration in a mouse model of colitis by regulating CXCL2 chemokine production in monocytes." (PMID 23631390, 2013). "In C57BL/6 mice, the transition from day 7 to 12 was characterised by high diarrhoea scores, increased weight loss, increased macroscopical signs of colitis and peak colon levels of IL-1β, CCL2, CXCL2/3 and CCL4." (PMID 22279558, 2012). "However, we did observe higher expression of key inflammatory cytokines (Il6, Il1b, Il17b) and chemokines (Cxcl1 and Cxcl2) involved in colitis in wild-type compared to R38E-PAR2 mice." (PMID 39171684, 2024). "The results showed that QYJD could reduce the content of chemokines CCL2 and CXCL2 in colonic tissue of mouse models of colitis induced by DSS." (PMID 36523417, 2022). "After 7 days of induced colitis, upregulation of the expression of 22 genes (Ccl2, Ccl3, Ccl4, Ccl5, Ccl6, Ccl7, Ccl12, Ccl17, Cxcl1, Cxcl2, Cxcl6, Cxcl9, Cxcl11, Ccr1, Ccr2, Ccr3, Ccr5, Ccr8, Cxcr2, Csf3, Osm, and Spp1) was observed in the CβG− group compared to the HβG- control group." (PMID 35163326, 2022).
colitis (continued). "Similar to our observations in human UC, there was significant upregulation of the neutrophil-active chemokines Cxcl1, Cxcl2, Cxcl3 and Cxcl5 across all models of colitis tested, indicating that this core chemokine module is conserved in colitis development across species." (PMID 36192482, 2022). "Another study revealed that early-life exposure to microbiota can induce microbial enduring and host changes that lead to colitis-associated cancer susceptibility, during which enhanced expression of CXCL1, CXCL2, and CXCL5 attracts G-MDSC to generate an immunosuppressive environment." (PMID 34689842, 2021). "In addition, the mRNA level of Cxcl2, a neutrophil-attracting chemokine, was enhanced after colitis was induced by DSS, and its expression level continued to be modulated 2 weeks after DSS administration was stopped (p < 0.001)." (PMID 34070845, 2021). "We found that there were 15 analytes upregulated in both DSS and C. rodentium colitis, including innate immune cell-associated cytokines (G-CSF, IL-1β, TNF-α, LIF, and IL-6), chemokines (CCL2, CCL5, CCL11, CXCL2, CXCL8, CXCL9, MIP-1α, and MIP-1β), and Th1 (IFN-γ) and Th17 (IL-17) cytokines." (PMID 30972302, 2019). "An attractive hypothesis is that EGFR signaling restricts epithelial CXCL2 expression, thereby limiting recruitment of neutrophils, key components of the immune infiltrate in colitis, after DSS-induced epithelial damage." (PMID 29904166, 2018). "Colons from p47phox−/− mice with DSS colitis were notable for significantly increased expression of granulocyte-colony stimulating factor (G-csf), chemokine (C-C motif) ligand 3 (Ccl3), and chemokine (C-X-C motif) ligand 2 (Cxcl2) compared to controls." (PMID 27044504, 2016). "Consistently, we found that the TTP KO mice treated with DSS displayed increased susceptibility to colitis, decreased colon length, and increased neutrophil infiltration and expression of pro-inflammatory cytokines such as TNF-α, IL-6, CXCL1, and CXCL2 in the large intestinal mucosa." (PMID 24586391, 2014). "Furthermore, the slight rise of pro-inflammatory factors like IL-6, CXCL1, and CXCL2 might suggest possible spontaneous colitis in a long observation period." (PMID 36425784, 2022). "However, the increase in Cxcl2 and Il-1β mRNA expression was significantly suppressed in the colons of IL-4Rα-/- colitis mice (Cxcl2; 5.3 ± 1.7 in WT colitis, 0.5 ± 0.3 in IL-4Rα-/- colitis; p < 0.05, Il-1β; 6.6 ± 2.1 in WT colitis, 0.3 ± 0.1 in IL-4Rα-/- colitis; p < 0.01)." (PMID 33192516, 2020). "Bulk RNA sequencing of colon tissues from FLNAR and FLNAQ animals on day 10 of DSS-induced colitis (the peak of disease) confirmed that FLNAR mice had less inflammation as indicated by a reduced expression of inflammatory genes (Il1b, Cxcl3, Cxcl2, or Trem1)." (PMID 40471139, 2025). "Similar to the reported effects of MSCs in chemically-induced colitis, BM-MSC treatments in Winnie mice downregulated the expression of Il6, Ifng, Il1b, Il1a, Tnf, Cxcl2, Tbx21 and Itgam, which were upregulated in Winnie mice and IBD patients." (PMID 38503815, 2024). "Studies conducted on mice with colitis have demonstrated that intact CPP is more efficacious in reducing the expression of pro-inflammatory factors IL-6, CXC motif chemokine ligand 2 (CXCL2), IL-1β, and TNF-α than a single CPP extract." (PMID 39839098, 2024). "In a mouse model of colitis, MACF1 KO resulted in increased TNF-α and increased MIP2/CXCL2 (macrophage inflammatory protein 2)." (PMID 37353479, 2023). "In comparison to the controls, mice with TNBS colitis and H4R knockout expressed higher levels of chemokines CXCL1 (KC) and CXCL2 (MIP2), IL-6, and the neutrophil enzyme myeloperoxidase (MPO)." (PMID 37373085, 2023). "The top 3 predicted upstream regulators in inactive extensive colitis were miR-155-5p, SOCS1, and TREM1, regulating CXCL2 and SOCS1; CXCL2 and SOCS1; and CXCL2, HES4, and TIFA, respectively." (PMID 32731480, 2020).
colitis (continued). "Among these analytes upregulated in colitis, the levels of G-CSF, CCL2, and CXCL2 were significantly reduced in mice on the ArgHIGH diet in the DSS model." (PMID 30972302, 2019). "In the current study, we detected a significantly higher colonic expression of Ccl2, Cxcl1, Cxcl2, and Cxcr3 genes in the control and RB groups (p < 0.05, RB vs. control) compared to the FRB group, which supports the protective effect of FRB in colitis." (PMID 28703759, 2017). "Our results showed that commensal bacteria induced the production of the chemokines CXCL1 and CXCL2, which induced the infiltration of Gr-1high/CD11bhigh neutrophils in the AOM/DSS-induced colitis." (PMID 27050089, 2016). "Other chemokines like CXCL1 and CXCL2, have previously been found up-regulated in TNBS-colitis and were up-regulated in our data." (PMID 23382912, 2013). "In the colitis model, the TRPM2 channel controls CXCL2 production in monocytes and consequently affects neutrophil infiltration, and in the lung inflammation model, TRPM2 plays a protective role by preventing ROS production in neutrophils." (PMID 23631390, 2013). "Knockout of CXCR2, which is the receptor of CXCL2 could protect mice against DSS-colitis-induced AKI and inflammation, indicating the therapeutic value of CXCL2 in AKI." (PMID 38753279, 2024). "However, only the expression of Cxcl2 and Ccl4 was markedly decreased in Npm1+/− ILC3s compared to WT ILC3s from mice with DSS-induced colitis." (PMID 39103576, 2024). "Interestingly, when we treated the infected colitis mice with LGG or BL, we observed a significant increase in IL-6, CXCL2, IL-1β, TNF-α, IL-17a, and IL-22 gene expression in the cecal tissue, indicating an enhanced inflammatory response." (PMID 38397855, 2024). "The chemokines CXCL1 and CXCL2 and their receptor CXCR2 play an important role in experimental colitis because the deletion of CXCR2 alleviates chronic colitis and associated tumors by inhibiting the penetration of myeloid derived suppressor cells (MDSCs) into the colon mucosa." (PMID 35163326, 2022). "Accordingly, we observed that the expression levels of genes encoding chemokines (Ccl3, Ccl4, and Ccl6), chemokine receptors (Ccr1, Ccr5, Cxcr2, Cxcl1, Cxcl2, and Cxcl13), and inflammatory factors (Mpo, Il-1β, and Il12) were increased in mice with DSS-induced colitis." (PMID 34795650, 2021). "Therefore, TRPM2-mediated Ca2+ influx is important in ROS-induced CXCL2/CXCL8 production by monocytes and neutrophil infiltration that, if heightened to colon inflammation, lead to colitis." (PMID 26300888, 2015). "In response to dextran sulfate sodium (DSS)-induced colon inflammation, a model of ulcerative colitis, there was strong increase in the CXCL2 expression in monocytes from the WT but not TRPM2-KO mice." (PMID 26300888, 2015). "Expression of Cxcl2 and Cxcl5, the proteins of which are known to target neutrophils and have suspected roles in IBD, was significantly increased in the DSS and TSR-treated mice during the acute phase of colitis." (PMID 22509329, 2012). "Our results demonstrated that the cecal gene expression of IL-6, CXCL2 (murine IL-8 homologue), IL-1β, TNF-α, IL-17a, IL-22, and CRAMP (homologue of human cathelicidin LL-37) was significantly elevated in the mice with P. aeruginosa-infected colitis after chemotherapy." (PMID 38397855, 2024). "The absence of GPR4 ameliorates colitis with lower histology scores, reduced CD4+ T helper cell infiltration, and decreased IFN-γ, iNOS, CXCL1, and CXCL2 expression." (PMID 35165253, 2022).